ADAM21 (ADAM metallopeptidase domain 21)
Description:
May be involved in sperm maturation and/or fertilization. May also be involved in epithelia functions associated with establishing and maintaining gradients of ions or nutrients.
Synonyms: ADAM 21; ADAM31
Tractability: Antibody: its Gene Ontology location is reachable by antibodies, with high confidence; UniProt predicts a signal peptide or a membrane-spanning region. PROTAC: ubiquitination databases record sites on it.
Gene: Protein-coding gene on chromosome 14 (70,417,107 to 70,460,427, forward strand). Ensembl gene ENSG00000139985.
Subcellular location: Membrane
Pathways (Reactome):
Reproduction: Interaction With Cumulus Cells And The Zona Pellucida
Gene Ontology:
Molecular function: protein binding; metalloendopeptidase activity; metallopeptidase activity
Biological process: male gonad development; proteolysis; single fertilization
Cellular component: external side of plasma membrane; plasma membrane; sperm head plasma membrane; axon; membrane; neuron projection; neuronal cell body
Genetic constraint (gnomAD): Loss-of-function variants: 1 observed, 0.75 expected, observed/expected ratio (o/e) 1.34, 90% interval 0.3 to 1.91. That is too few expected variants to judge how well the gene tolerates losing a copy. Missense variants: 671 observed, 858.29 expected, observed/expected ratio (o/e) 0.78, 90% interval 0.73 to 0.83. Synonymous variants: 259 observed, 295.82 expected, observed/expected ratio (o/e) 0.88, 90% interval 0.79 to 0.97.
Homologues: Orthologues: macaque ADAM21 (95% identical), dog ADAM21 (76% identical), pig ADAM21 (74% identical), rabbit ADAM21 (72% identical), mouse Adam21 (68% identical), rat LOC103690152 (67% identical), chimpanzee ADAM21 (61% identical), tropical clawed frog XB990656 (32% identical), zebrafish adam9b (31% identical), Caenorhabditis elegans unc-71 (27% identical), Drosophila melanogaster mmd (20% identical), zebrafish adam10a (20% identical), and 4 more. Paralogues in human: ADAM20 (61% identical), ADAM29 (49% identical), ADAM30 (39% identical), ADAM9 (36% identical), ADAM19 (29% identical), ADAM33 (29% identical), ADAM12 (29% identical), ADAM22 (28% identical), ADAM2 (28% identical), ADAM11 (27% identical), ADAM15 (27% identical), ADAM23 (27% identical), and 8 more.
Diseases named in the same sentence as ADAM21 in open-access papers:
ADAM21 is named in the same sentence as 10 diseases in open-access papers, as found by Europe PMC text mining. Sharing a sentence is not in itself a finding about the gene and the disease. The quoted sentences say what the papers report.
Cirrhosis (1 paper, 2017). A chronic disorder of the liver in which liver tissue becomes scarred and is partially replaced by regenerative nodules and fibrotic tissue resulting in loss of liver function. "A univariate analysis revealed that cirrhosis (P = 0.026), serum AFP levels (P = 0.003), number of hepatic tumors (P < 0.001), and ADAM21 positivity (P < 0.001) were prognostic factors for recurrence-free survival (RFS)." (PMID 29138461, 2017).
glioma (1 paper, 2025). A benign or malignant brain and spinal cord tumor that arises from glial cells (astrocytes, oligodendrocytes, ependymal cells). "The candidate interactors were compiled from BioGRID‐curated BioPlex AP‐MS performed in non‐glioma cell lines (HEK293T/HCT116), and one (ADAM21) is from a pre‐publication dataset." (PMID 41354084, 2025).
Infertility (1 paper, 2021). "To investigate whether Adam21−/− mice were fertile, we conducted a fertility test of Adam21−/− mice and Adam21+/− mice, and found that neither male nor female Adam21−/− mice displayed any infertility, they produce similar amount of litter to that of the control mice." (PMID 34631320, 2021).
tumor (3 papers, 2017 to 2024). "Each of the three genes (RHPN2, MUC4 or ADAM21) that harbored mutations in more than one tumor has a regulatory role in cell adhesion and motility, cell functions essential to the metastatic process." (PMID 29259192, 2017). "In clinical specimens, ADAM21 positivity was associated with vascular invasion, large tumor size, high histological grade, and lower overall and recurrence-free survival as compared to cases that were negative for ADAM21 expression." (PMID 29138461, 2017). "Conversely, ADAM7 and ADAM21 displayed lower levels of methylation in tumor tissues compared to normal tissues." (PMID 39346916, 2024). "ADAM21 protein was detected in the cytoplasm of tumor cells and exhibited various staining patterns." (PMID 29138461, 2017). "Our clinicopathological study showed that high ADAM21 expression level in HCC tumors is closely related to large tumor size, high histological grade, and presence of vascular invasion and is an independent risk factor for poor OS and RFS." (PMID 29138461, 2017). "One possible mechanism is the paracrine stimulation of adjacent non-neoplastic hepatocytes by unidentified factors that upregulate ADAM21 production by tumor cells." (PMID 29138461, 2017). "Our analysis of tissue samples from HCC patients undergoing curative resection showed that ADAM21 expression varied, and was present not only in tumor cells but also in adjacent non-neoplastic hepatocytes." (PMID 29138461, 2017).
ADAM21 also shares sentences with these, for which no sentence is quoted: cancer (2 papers); astrocytic tumor (1); brain tumor (1); colon cancer (1); connective tissue disorder (1); varicocele (1).